XPA (XPA, DNA damage recognition and repair factor)
Diseases named in the same sentence as XPA in open-access papers (continued):
Sharing a sentence is not in itself a finding about the gene and the disease.
colon cancer (3 papers, 2012 to 2022). "In HCT116 colon cancer cells we had previously found within 1h of GZ17-6.02 exposure that the expression of XPA and XPD had declined and the levels of RAD51 and RAD52 were enhanced." (PMID 36408163, 2022). "Subgroup analysis based on age and tumor location suggested consistently significant down‐regulation of XPA in CRC tissues than in their adjacent tissues in age > 60 (P = 0.026), age ≤ 60 (P = 0.008), colon cancer (P = 0.009), and rectal cancer (P = 0.015)." (PMID 29675892, 2018). "Subgroup analysis indicated consistently significant down‐regulation of XPA in CRC tissues in age > 60 (P = 0.026), age ≤ 60 (P = 0.008), colon cancer (P = 0.009), and rectal cancer (P = 0.015) patients and males (P = 0.004)." (PMID 29675892, 2018).
hearing loss (3 papers, 2017 to 2025). "The representative manifestation of hearing impairment in patients with XP-A harboring a homozygous IVS3-1G>C missplice mutation of XPA is bilateral severe to profound hearing loss; the audiogram is usually horizontal or worse at higher frequencies." (PMID 28239347, 2017). "A heterozygous pathogenic variant In XPA was detected in patient HA106, a 47 year-old male diagnosed with ataxic gait, cerebellar atrophy, unilateral hearing loss and cognitive impairment." (PMID 40208338, 2025). "However, in XPA, XPB, XPD and XPG, more than 50.0% of patients with abnormal audiograms presented with moderate-severe hearing loss." (PMID 38040034, 2023).
nasopharyngeal carcinoma (3 papers, 2015 to 2020). A carcinoma arising from the nasopharyngeal epithelium. "The XPA expression was also detected in cancer tissues from locally advanced nasopharyngeal carcinoma (NPC) patients treated with platinum-based chemoradiotherapy to examine if it is a prognostic factor." (PMID 32235701, 2020). "As the one of the toughest challenges for cancer treatment, chemotherapeutic resistance for platinum has been detected in XPA‐overexpressed nasopharyngeal cancer." (PMID 29675892, 2018).
progeria (3 papers, 2008 to 2024). "Further, tools such as this can identify patterns not previously recognized in known progerias, for instance we observe that XPA, CS and AT cluster closely together while XPB and XPG that in rare cases can lead to a CS like phenotype are in a separate, but associated, cluster." (PMID 38345566, 2024).
Ataxia (2 papers, 2013 to 2017). Ataxia refers to impaired coordination of voluntary muscle movement. "In an XPA-deficient spinocerebellar ataxia (SCA1) mouse model, (CAG) repeats were stabilized in certain neuronal cell types, and XPA can bind to hairpin DNA in vitro." (PMID 23620289, 2013).
ataxia telangiectasia (2 papers, 2016 to 2021). Ataxia-telangiectasia is the association of severe combined immunodeficiency (affecting mainly the humoral immune response) with progressive cerebellar ataxia. "XPA-iPSCs exhibited hypersensitivity to ultraviolet exposure and accumulation of single-nucleotide substitutions when compared with ataxia telangiectasia-derived iPSCs that were established in a previous study." (PMID 27197874, 2016).
Cognitive impairment (2 papers, 2023 to 2025). Abnormal cognition is characterized by deficits in thinking, reasoning, or remembering. "Cognitive impairment was a frequent feature in XPD, XPG and XPA." (PMID 38040034, 2023).
Erythema (2 papers, 2018 to 2024). Redness of the skin, caused by hyperemia of the capillaries in the lower layers of the skin. "The inactivation of XPA disrupted the repair activity on the DNA-distorting lesions, which resulted in erythema, blisters, and lentiginous pigmentation in the exposed areas, as well as stunted physical and cognitive development." (PMID 39129919, 2024).
glioblastoma (2 papers, 2022 to 2024). The most malignant astrocytic tumor (WHO grade IV). "In addition, XPA enhances temozolomide resistance in glioblastoma cells by promoting nucleotide excision repair." (PMID 36509750, 2022).
lung adenocarcinoma (2 papers, 2011 to 2020). A carcinoma that arises from the lung and is characterized by the presence of malignant glandular epithelial cells. "We next investigated whether we could exploit the ASL relationship between XPA and MK2 for treatment of murine lung adenocarcinomas using our nanoplexes to co-deliver siRNAs against both MK2 and XPA in vivo." (PMID 32807787, 2020).
lymphoma (2 papers, 2016 to 2018). A malignant (clonal) proliferation of B- lymphocytes or T- lymphocytes which involves the lymph nodes, bone marrow and/or extranodal sites. "The lymphatic system, including the spleen, is also a target organ for tumors (lymphomas) in orally exposed MutaMouse, and XPA-deficient mice (IARC." (PMID 29177888, 2018).
oral squamous cell carcinoma (2 papers, 2016 to 2023). "The study results of SNP 10817938 for the Saudi population are inconsistent with the study that confirmed the association of XPA polymorphisms with oral squamous cell carcinoma (OSCC) risk in the Han Chinese population." (PMID 37510255, 2023). "However, the role of XPA polymorphisms in patients with oral squamous cell carcinoma (OSCC) remains unclear." (PMID 27622501, 2016).
osteosarcoma (2 papers, 2019 to 2025). A usually aggressive malignant bone-forming mesenchymal neoplasm, predominantly affecting adolescents and young adults. "Notably, ERCC8 and XPA have been previously implicated in DDP resistance, and we also demonstrated that they regulated the sensitivity of osteosarcoma cells to DDP treatment." (PMID 40019400, 2025).
rectal cancer (2 papers, 2018). A primary or metastatic malignant neoplasm that affects the rectum. "In rectal cancer, high XPA expression predicted worse TNM stage, T stage, and N stage." (PMID 29568775, 2018). "High expression of XPA protein showed significant relationship with better survival of CRC, especially rectal cancer." (PMID 29675892, 2018). "For rectal cancer, ERCC2 expression correlated with favourable T stage; XPA expression predicted worse TNM stage." (PMID 29568775, 2018). "For rectal cancer, significant relation was observed between ERCC2 high expression and favourable T stage (P = 0.019); high XPA expression obviously predicted worse TNM stage (P = 0.025), T stage (P = 0.019), and N stage (P = 0.008)." (PMID 29568775, 2018).
testis tumor (2 papers, 2011 to 2020). "In fact, supplementing cell extracts isolated from testicular tumor cells with purified XPA protein can restore the repair activity for cisplatin damage, implying that the low repair capacity is due to insufficient XPA protein in these cancer cells." (PMID 33291532, 2020). "XPA protein levels are significantly low in metastatic testicular tumor cells, which is consistent with positive response to cisplatin and excellent prognosis for TGCT patients." (PMID 33291532, 2020). "This is consistent with reports that have shown significantly lower levels of ERCC1, XPF, and XPA protein in testis tumor cell lines do not cohere with the transcriptional efficiency or mRNA stability of the cognate factors." (PMID 21385444, 2011). "In addition, increasing XPA levels in testicular tumor cells by a 10-fold did not increase resistance to cisplatin." (PMID 21385444, 2011).
anemia (1 paper, 2024). A reduction in the number of red blood cells, the amount of hemoglobin, and/or the volume of packed red blood cells. "However, the role of FA detoxification is strikingly relevant in cells with mutations in Fanconi anemia (FANCA) and in genes coding for the NER factors CSB and XPA." (PMID 38894680, 2024).
autism spectrum disorder (1 paper, 2012). A spectrum of developmental disorders that includes autism, and Asperger syndrome. "Those early reductions in FA in the brain of XPA are consistent with those in other congenital developmental disorders such as Prader–Willi syndrome or autism spectrum disorder." (PMID 22574268, 2012).
bladder tumors (1 paper, 2021). "However, our results show that the levels of both XPA and TAp63 in bladder tumors isolated from T3/T4 patients are relatively low compared to those in T1/T2 and Ta patients." (PMID 34747697, 2021).
cervical cancer (1 paper, 2022). A primary or metastatic malignant neoplasm involving the cervix. "Univariate Cox regression analysis screened 7 genes (FZR1, IMPDH1, HNRNPCL2, PCNA, GPKOW, XPA, and DDX39A) that were associated with the cervical cancer prognosis." (PMID 35909901, 2022). "Identification of KIN-related prognostic genes in cervical cancer revealed that a total of 5 genes (FZR1, IMPDH1, GPKOW, XPA, and DDX39A) were constructed for this risk score, and the results showed that CTLA4 expressions were negatively correlated with the risk score." (PMID 35909901, 2022).
choriocarcinoma (1 paper, 2020). An aggressive malignant tumor arising from trophoblastic cells. "The highest XPA and ERCC1 expression was found in TE, with decreasing amounts in yolk sac tumours and choriocarcinoma." (PMID 31906898, 2020).
hereditary cancer (1 paper, 2020). Malignant neoplasms occurring in families at a rate greater than that expected by chance and caused by germline mutations in a specific gene. "In addition to mutations associated with risk of hereditary cancer, pathogenic/likely pathogenic mutations were detected in ERCC2 (n = 1), FANCA (n = 1), FANCC (n = 1), HNF1A (n = 1), PRF1 (n = 1) RECQL4 (n = 2), WRN (n = 1), and XPA (n = 1)." (PMID 31963545, 2020).
Hutchinson-Gilford progeria syndrome (1 paper, 2014). "XPA has been showed to be involved in the mechanism of HGPS (Hutchinson-Gilford progeria syndrome) by binding to aberrant DNA replication forks in HGPS cells; a recent finding suggests that XPA deficiency may lead to mitochondrial dysfunction." (PMID 25385088, 2014).
Hyperglycemia (1 paper, 2021). An increased concentration of glucose in the blood. "The recognition that NER genes including XPC, XPA, XPD, CSA, CSB, and XPG possess HREs prompted us to interrogate whether hyperglycemia-induced destabilization of HIF-1α contributed to NER attenuation." (PMID 34426491, 2021).
laminopathy (1 paper, 2009). A rare genetic disorder caused by mutations in genes encoding proteins of the nuclear lamina. "Howdoes the binding of XPA to laminopathy-generated DSBs relate to the lack ofRad50 and Rad51 binding?" (PMID 19851476, 2009). "Whydoes XPA colocalize with the laminopathy-induced DSBs marked by γ-H2AX inaging progeroid cells?" (PMID 19851476, 2009).
laryngeal carcinoma (1 paper, 2018). Carcinoma that arises from the laryngeal epithelium. "Polymorphisms in other NER genes including ERCC1, ERCC2, ERCC3, ERCC4, ERCC5, and XPA have also been reported to pose as an increased risk in Laryngeal Cancer." (PMID 30410671, 2018).
leukemia (1 paper, 2011). A malignant (clonal) hematologic disorder, involving hematopoietic stem cells and characterized by the presence of primitive or atypical myeloid or lymphoid cells in the bone marrow and the blood. "Analysis of leukemia-prone polymorphic alleles (XPA A23G, XPD Lys751Gln, XRCC1 Arg399Gln, XRCC3 Thr241Met, and RAD51 G135C) revealed an XPD and XRCC3-deficient heterozygous pre-SCT patient with normal alleles for XPA, XRCC1, and RAD51 DNA repair functions." (PMID 21951951, 2011).
metastatic tumors (1 paper, 2011).
myocardial infarction (1 paper, 2023). Gross necrosis of the myocardium, as a result of interruption of the blood supply to the area, as in coronary thrombosis. "In contrast, reduced expression of numerous DNA repair genes, including ERCC1, XPA, and ATM, are associated with stable angina and myocardial infarction." (PMID 36734200, 2023).
pneumonia (1 paper, 2021). An acute, acute and chronic, or chronic inflammation focally or diffusely affecting the lung parenchyma, caused by an infection in one or both of the lungs (by bacteria, viruses, fungi, or mycoplasma.). "XPa protected mice in pneumonia models from infection with PAO1 or multidrug-resistant clinical isolate W9." (PMID 34593766, 2021).
pterygium (1 paper, 2010). A wedge-shaped fibrovascular lesion arising from the bulbar conjunctiva and extending to the cornea. "Because the polymorphism of hOGG1 was reported to be associated with pterygium, it is logical to assume the correlation between XRCC1, XPA, and XPD polymorphisms and pterygium formation." (PMID 20431719, 2010). "In the present study, we conducted a case control study to evaluate the associations of pterygium formation and XRCC1 codon 107, 194, 280, and 399; XPA A23G; XPA codon 228; and XPD codon 751 polymorphisms." (PMID 20431719, 2010). "This is the first case-control study of polymorphisms in XRCC1 codon 107, 194, 280, and 399; XPA A23G; XPA codon 228; and XPD codon 751 in relation to pterygium formation." (PMID 20431719, 2010). "We suggest that the different result may be due to the following three possibilities: First, it is other polymorphisms in XPA and XPD and not the XPA A23G, XPA codon 228, and XPD codon 751 polymorphisms that are involved in pterygium formation." (PMID 20431719, 2010). "However, XPA and XPD— NER system genes—are not found to be associated with pterygium in our series." (PMID 20431719, 2010). "Second, it is other genes in NER, not XPA or XPD, that are involved in pterygium formation." (PMID 20431719, 2010).
seminoma (1 paper, 2013). A radiosensitive malignant germ cell tumor found in the testis (especially undescended), and extragonadal sites (anterior mediastinum and pineal gland). "The detection of proteins SCP1 and XPA, which are normally expressed in the primary and pachytene spermatocyte stages, provide a clue that the origin of SS is in a more differentiated cell than in classical seminoma." (PMID 23915031, 2013).
testicular germ cell tumour (1 paper, 2022). "In line with this assumption, we have recently showed that the testicular germ cell tumour (TGCT) patients with low XPA expression have better OS than patients with high expression of this protein." (PMID 36293346, 2022).
cancer (44 papers, 2010 to 2026). A tumor composed of atypical neoplastic, often pleomorphic cells that invade other tissues. "Using the tumour suppressor gene XPA as an example, we directly show that a cancer-specific single-nucleotide mutation disrupting the PAS hexamer is sufficient to block pre-mRNA cleavage/polyadenylation and dampen the expression of mature mRNA." (PMID 39660592, 2024). "Accumulating evidence showed that XPA protein is closely associated with chemotherapy and radiotherapy resistance in cancer patients." (PMID 36509750, 2022). "Higher XPA expression is usually associated with poor prognosis in multi-types of human cancers, representing a potential target for anti-cancer therapy." (PMID 36509750, 2022). "It has been found that the RASSF1A A133S variant associates with several cancers, and at the same time, this variant inhibits XPA deacetylation, stabilizes the XPA–RASSF1 complex, and decreases DNA repair." (PMID 36496984, 2022). "We failed to obtain evidence regarding the relationship between the XPA rs1800975 polymorphism and the overall risk of cancer in the overall population." (PMID 32435155, 2020). "We were interested in comprehensively exploring the impact of XPA rs1800975 on overall cancer susceptibility by pooling all currently available evidence." (PMID 32435155, 2020). "Changes in the expression level of XPA are assumed to significantly contribute to cancer risk, disease prognosis and treatment outcome." (PMID 32235701, 2020). "To date, there are only two reported meta-analyses from 2012 describing the association between XPA rs1800975 and susceptibility to overall cancer diseases." (PMID 32435155, 2020). "There are different reports with distinct conclusions regarding the genetic relationship between the XPA rs1800975 polymorphism and cancer susceptibility in varied populations." (PMID 32435155, 2020). "We found that 148Asp/Glu polymorphism of APEX gene and 23Gly/Ala polymorphism of XPA gene are increasing the risk of cancer in the second degree of advancement in relation to the first degree." (PMID 28386271, 2017). "Among the known polymorphisms of the DNA repair genes, the polymorphisms of ERCC4 and XPA genes from NER pathway have been repeatedly studied as potentially connected with susceptibility to the occurrence of various cancers." (PMID 28386271, 2017). "Single nucleotide polymorphisms of XPA gene have been studied in several cancers such as rs10817938, rs2808668." (PMID 27622501, 2016). "Resistance of XPA-deficient lymphoblastoid cells to H2O2-induced cell death while harbouring DNA damage poses a potential cancer risk factor for XPA patients." (PMID 21176161, 2010). "A meta-analysis indicated that XPA is a minor risk factor for the development of cancer." (PMID 38541204, 2024). "Given that, the XPA polymorphisms are related to the risk of many types of cancers." (PMID 37510255, 2023). "The results of the study indicate that gender may have a significant role in the association between the XPA rs3176751 polymorphism and the cancer risk or other diseases." (PMID 37510255, 2023). "It is interesting to see contrasting results among different kinds of cancer, suggesting the susceptibility of XPA rs1800975 to cancer risk may be dependent on cancer type." (PMID 27768589, 2016). "In addition to rs1800975, recent studies have indicated a potential association of a novel promoter polymorphism (rs10817938) in the XPA loci and cancer development." (PMID 27622501, 2016). "This polymorphism has not been evaluated to be associated with the risk of any disease, but another XPA promoter SNP located at −4 bp might change XPA mRNA tertiary structure and stability, and might play a role in susceptibility to cancer." (PMID 26967386, 2016). "In other cancers with tumor samples taken prior to cisplatin treatment, a high expression of XPA has been correlated with decreased OS." (PMID 39001501, 2024).